TNF (tumor necrosis factor)
Diseases named in the same sentence as TNF in open-access papers (continued):
Sharing a sentence is not in itself a finding about the gene and the disease.
COVID-19 (continued). "The analyses of three large databases of individuals with immune-mediated inflammatory diseases have demonstrated an inverse association of anti-TNFα use and COVID-19-related outcomes, but further clinical trials are needed." (PMID 35164139, 2022). "This meta-analysis analyzed the association between the levels of TNF-α, IL-6, and vitamin D and the severity and mortality of COVID-19." (PMID 35215138, 2022). "Among others, IL-6 and TNF-α are over-expressed in COVID-19 while the IL-1 family is strongly associated with acute inflammation." (PMID 36037223, 2022). "Serum cytokine levels that are elevated in patients with COVID-19-associated cytokine storm include interleukin-1β, interleukin-6, IP-10, TNF, interferon-γ, macrophage inflammatory protein (MIP) 1α and 1β, and VEGF." (PMID 35353232, 2022). "Although TNF antagonist and immunosuppressive thiopurine treatment was associated with risk of hospitalization or death from COVID-19, TNF antagonist treatment alone was associated with lower odds ratios of hospitalization or death." (PMID 36032119, 2022). "BALB/c mouse COVID-19 (mCOVID-19) is associated with an increased NK cell and interferon response and is ameliorated by IFNγ and TNF blockade." (PMID 35023830, 2022). "TNF-α has also been reported to induce expression of NOTCH1 and NOTCH4 and high serum TNF-α levels are associated with increased mortality in severe COVID-19." (PMID 35992174, 2022). "IL-6 and tumor necrosis factor (TNF)-α participate in COVID-19-induced cytokine storm, causing endothelial cell damage and upregulation of plasminogen activator inhibitor-1 (PAI-1) levels." (PMID 35784318, 2022). "High levels of pro-inflammatory cytokines such as interleukin (IL)-1β, IL-2, IL-6, IL-7, IL-8, IL-17, and tumor necrosis factor-α (TNF-α) have been reported in the serum of patients with severe COVID-19, which is associated with mortality risk." (PMID 35255966, 2022). "Increased plasma levels of TNF-α in COVID-19 are associated with disease severity and inversely correlate with the reduction in T lymphocytes." (PMID 36016267, 2022). "There were 6 studies that analyzed the association between the TNF-α level and severe COVID-19; these reported an odds ratio (OR) value from a logistic regression analysis with the TNF-α level as a continuous variable." (PMID 35215138, 2022). "The TNFα.− 308A allele has an influence on developing symptoms of COVID-19 in Cuban patients, and that it particularly increases the risk of presenting severe forms of the disease in the eastern region of the country." (PMID 37521833, 2022). "Among cytokines, interleukin 6 (IL-6), TNF and IL-1β have been identified as key targets associated with PF secondary to COVID-19." (PMID 35308222, 2022). "In turn, the level of TNF-α is associated directly with the probability of hospitalization and severe COVID-19." (PMID 35883738, 2022). "A total of 22 studies analyzed the association between TNF-α, IL-6, and vitamin D levels and the severity of COVID-19." (PMID 35215138, 2022). "Recent studies on COVID-19 suggest that cytokine release syndrome is associated with the severity of disease; this syndrome is characterized by increased TNF-α, interleukin (IL)-6, IL-2, IL-7, and IL-10." (PMID 36361745, 2022). "In a recent cohort study, TNF-α inhibitor monotherapy was found to reduce risk in severe COVID-19 patients." (PMID 35992174, 2022). "Among these, changes in IL-6, IL-1β and TNF-α levels were the best documented in the hyperinflammatory response associated to COVID-19 and ARDS." (PMID 36466830, 2022). "The results of the meta-analysis were that each increase in the TNF-α level of 1 pg/mL significantly increased the risk of mortality of COVID-19 patients (crude HR = 1.0640; 95% CI 1.0259–1.1036; p = 0.0009)." (PMID 35215138, 2022). "Increased circulating levels of proinflammatory cytokine, including IL-10, IL-6, and TNF-α, have been reported to be associated with severe COVID-19." (PMID 35172892, 2022).
COVID-19 (continued). "Exposure to TNF alpha inhibitors reduced the risk of COVID-19-associated hospitalization compared to methotrexate and ustekinumab, but not with acitretin." (PMID 35566548, 2022). "Previous studies have shown that increased interleukin (IL)-6 and tumor necrosis factor alpha (TNFα), along with T helper 1-specific cytokines such as interferon-induced protein 10 (IP-10), are associated with severe COVID-19 response and mortality." (PMID 36865568, 2022). "A recent study by Del Valle and colleagues showed that elevated levels of immune-biomarkers involved in the cytokine storm induced by COVID-19 at the time of hospitalization, like both IL-6 and TNF-α, were significantly associated with patients’ survival." (PMID 35453526, 2022). "ALI caused by cytokine storm is the characteristic of COVID-19, and only the combination of TNF-α (an important subtype of TNF signaling pathway) and IFN-γ can induce inflammatory cell death during SARS-CoV-2 infection." (PMID 35754492, 2022). "Laboratory abnormalities observed in adults, including elevated levels of D-dimers and cytokines (IL-6, IL-10, TNF-alpha), have been associated with severe COVID-19 courses and increased mortality." (PMID 35546159, 2022). "Elevated serum levels of IL-6, IL-8, IL-1β, and TNF-α correlate with moderate and severe COVID-19, while IL-12p70 and IL-2 serum expression is associated with asymptomatic and mild diseases." (PMID 36526691, 2022). "Elevated pro-inflammatory cytokines, including IL-17 and TNF-α, were the main causes of disease deterioration in COVID-19 patients." (PMID 35677450, 2022). "TLR4-mediated production of IL-6 and TNF-α is associated with the severity of COVID-19 in patients with cardiometabolic comorbidities." (PMID 35356515, 2022). "Multiple intracellular transductions, such as TNF-alpha, mTOR, NF-κB, etc., are implicated in the pathogenesis of COVID-19." (PMID 35992697, 2022). "A great deal of data showed that TNF-α has a receptor association with COVID-19 and higher TNF-α expression is correlated with disease severity and higher mortality." (PMID 34063739, 2021). "In our analysis we observed that several biomarkers, including GM-CSF, MCP-1, MIP1α, TNFα, IL-1RA, IL-6, IL-8, IL-15 and IL-10 were associated with fatal outcomes in COVID-19." (PMID 34539631, 2021). "Lymphocyte apoptosis develops secondary to increased TNF-α and IL-6 levels in a cytokine storm, and COVID-19 causes down-regulation in genes that cause T lymphocyte proliferation." (PMID 34784756, 2021). "Elevated levels of TNFα and other pro-inflammatory cytokines and chemokines, such as IL-6, IL-10 are risk factors for the development of severe COVID-19, and their levels are much higher in critical patients than in those with milder disease." (PMID 33465050, 2021). "In some patients, COVID-19 causes multiorgan failure; however, anti-TNF therapy has a wide margin of safety because it is eliminated from the body via the reticuloendothelial system, requiring no dose titration steps." (PMID 33714258, 2021). "Increased levels of IFN-γ, IP-10, MCP-1 and TNF-α are associated with severity of disease in COVID-19 patients." (PMID 33465158, 2021). "Is receipt of tumor necrosis factor (TNF) inhibitor monotherapy at the time of COVID-19 diagnosis associated with adverse COVID-19 outcomes compared with other treatment regimens among patients with immune-mediated inflammatory diseases (IMIDs)?" (PMID 34661663, 2021). "In this cohort study, TNF inhibitor monotherapy was associated with a lower risk of adverse COVID-19 outcomes compared with other commonly prescribed immunomodulatory treatment regimens among individuals with IMIDs." (PMID 34661663, 2021). "Pooling data across registries offers an opportunity to rapidly assess any association between TNF inhibitor therapies and COVID-19 outcomes among individuals with IMIDs and to evaluate the consistency of findings across studies and diseases." (PMID 34661663, 2021).
COVID-19 (continued). "Among the proinflammatory cytokines (IL-1β, TNF-α, IL-8, and IL-6) analyzed herein, TNF-α was seen as a risk factor for the death of patients with severe or critical COVID-19." (PMID 34725309, 2021). "Consistent with published studies, we observed high concentrations of inflammation-associated cytokines, including IL-6, TNF-α, IP-10, IL-10, IL-1α and IL-1β, in serum and nasal lining fluid from PCR-confirmed COVID-19 patients." (PMID 34117221, 2021). "Recent clinical reports have shown that inflammation was induced in COVID-19 cases, and this induction was associated with an increased level of cytokines, including interleukins (IL-1β, IL-6, IL-10) and tumor necrosis factor-α (TNF-α)." (PMID 34901061, 2021). "The coronavirus disease 2019 (COVID-19) is associated with cytokine dysregulation, increased IL-1β, tumor necrosis factor (TNF) and IL-6 release with hyperinflammation and risk of CSS." (PMID 33562758, 2021). "Serum TNF-α level was found to be an independent risk factor for the mortality of patients with severe or critical COVID-19." (PMID 34725309, 2021). "All of these cytokines (TNFα, IL-1β, IL-6) were found in high levels in COVID-19 patients and associated with severe disease outcomes." (PMID 34163462, 2021). "In the context of COVID-19, early registry data have shown anti-TNF therapy to be associated with a decreased odds of hospitalization due to COVID-19." (PMID 33710296, 2021). "It is also observed that aged persons are prone to develop B—lymphocytes (double-negative B cells) that are able to secrete pro-inflammatory mediators such as TNF-α, IL-6 and IL-8 and have been implicated in clinical manifestation of COVID-19." (PMID 35010301, 2021). "A study that enrolled 548 patients found that high cytokine levels (IL-2R, IL-6, IL-10, and TNF-α) were significantly associated with severe COVID-19 on admission, whose findings correspond with our results." (PMID 34489933, 2021). "Most recently, IFN-γ/TNF-α synergy was causally implicated in macrophage PANoptosis in the context of COVID-19." (PMID 34556638, 2021). "As a result, higher and lower levels of TNF-α after day 3 are associated with poor and good COVID-19 outcomes, respectively." (PMID 35126355, 2021). "IFN-γ, TNF, IL-6, and IL-8 levels were significantly increased in COVID-19 patients, causing pregnant women with COVID-19 to be more prone to miscarriage and premature rupture of membranes." (PMID 34458162, 2021). "For instance, we discovered that JAK-STAT, NFKβ, TGFβ, TNFα, and Hypoxia pathways are central players underlying and differentiating the COVID-19 pathophysiology, as their tendency is opposite between moderate and severe patients." (PMID 34603282, 2021). "The tumor necrosis factor alpha (TNF-α) is a proinflammatory cytokine released by macrophages causing vascular leakage, edema and lung injury in COVID-19." (PMID 34178414, 2021). "After an inflammatory trigger, the mechanism for activation of the coagulation cascade in COVID-19 is the tissue factor pathway, which causes endotoxin and tumor necrosis factor-mediated production of interleukins and platelet activation." (PMID 33401632, 2021). "Our in silico results have evidenced affinity between mullein phytochemicals (Flavones and O-metilated flavones) and pro-inflammatory cytokines (IL-2 and TNF-α), molecules implicated in inflammatory processes related to the respiratory system and COVID-19." (PMID 34356473, 2021). "The magnitude of senescence led to a high surge of IL6, IL1b, IFNγ, C-reactive protein, and TNFα is reported in several epidemiological studies to lower airway and lung injury and risk for in COVID-19 elderly patients." (PMID 33815889, 2021). "Our in vitro study has shown that CVL218 can effectively inhibit the production of several inflammatory cytokines induced by LPS in PBMCs, including IL-6, IL-10, IFN-γ, and TNF-α, which are highly related to the pathogenic characteristics of COVID-19." (PMID 33895786, 2021).
COVID-19 (continued). "An exaggerated inflammatory response is the primary driver of poor COVID-19 outcomes, and higher levels of TNF, a proinflammatory cytokine, have been linked to increased COVID-19 mortality." (PMID 33714258, 2021). "This includes for example therapeutic antibodies interfering with either IL1β, IL6, TNFα or their receptors directly contributing to the CRS associated with severe COVID-19." (PMID 34293006, 2021). "Serum cytokine levels that are elevated in patients with COVID-19-associated cytokine storm include IL-1β, IL-6, TNF, IFN-γ and MIP-1." (PMID 33397398, 2021). "The possibility of interrupting thiopurine therapy in patients at high risk for COVID-19 with disease in remission phase on therapy with thiopurine + anti-TNF has been proposed." (PMID 34572185, 2021). "We concluded that serum TNF-α level acts as an independent risk factor for the mortality of severe and/or critical COVID-19 patients." (PMID 34725309, 2021). "The emerging literature data from recently published clinical trials on severe COVID-19 patients revealed that high circulating levels of IL-6, IL-1β, IL-8 and TNF-α were associated with poor prognosis and higher mortality rates." (PMID 34207266, 2021). "In severe cases of COVID-19, high levels of TNF-α, IL-1 and IL-6 are associated with coagulation activation and thrombin generation, leading to disseminated intravascular coagulation or thrombotic complications." (PMID 33916917, 2021). "These cytokines, such as IL-6, IL-7, CCL-2/MCP-1, CCL-3/CCL-4 MIP-1α/β, TNF-α, and G-CSF, have been implicated in COVID-19 pathogenesis." (PMID 34341347, 2021). "Here, the lower expression of DUSP1 observed in SARS-CoV-2 infected cells and nasopharyngeal swabs of severe COVID-19 patients was associated with the higher expression of TNF-α, IL-1β, and IL-1A genes (respectively)." (PMID 33995033, 2021). "Elevated levels of TNF-α and IL-6 are associated with severe cases of COVID-19 and systemic inflammation, as well as HSPA1L gene upregulation via hypomethylation of its promoter regions in response to increased SARS-CoV-2 viral replication." (PMID 34691068, 2021). "A subsequent study reported that combination therapy with anti-TNF and thiopurine (OR: 4.01, 95% CI: 1.65–9.78) was associated with an increased risk of severe COVID-19." (PMID 34858891, 2021). "TNF-α level was also turned out to be associated with the severity of COVID-19 patients (1.300 [1.086–1.556]; p = 0.004; 1.476 [1.136–1.919]; p = 0.004)." (PMID 34725309, 2021). "Anti-TNF therapy or TNF-α blockers are important to reduce inflammation-driven capillary leak caused by the key inflammatory cytokines which deteriorates the lung function of COVID-19 patients." (PMID 33858291, 2021). "The NLRP3 is activated through the oxidized LDL and TNF α, causing cytokine storms and cardiac complications in COVID-19 patients." (PMID 34604534, 2021). "The COVID-19-associated cytokine storm is associated with elevated plasma levels of IL-6, IL-1 and TNF-α, as well as of ferritin and other inflammatory biomarkers." (PMID 34441796, 2021). "For example, the use of TNF inhibitors has been associated with protection from severe COVID-19, while most of the disease-modifying anti-rheumatic drugs (DMARDS) do not seem to confer increased risk." (PMID 34512643, 2021). "Among the reported cytokines, tumor necrosis factor-alpha (TNF-α) has been associated as a key component of the cytokine storm observed in many COVID-19 patients." (PMID 34576032, 2021). "Data from the SECURE-IBD reported that compared with TNFα antagonist monotherapy, thiopurine monotherapy and combination therapy with TNFα antagonist and thiopurine were associated with an increased risk of severe COVID-19." (PMID 33761992, 2021). "A hospital-based case-control study comparing COVID-19 patients with controls described the frequency of −308 (G/A) TNF-α polymorphisms." (PMID 33807915, 2021).
COVID-19 (continued). "We identified Fcγ Receptor (FcγR) IIa and FcγRIII as the two primary IgG receptors that are responsible for the induction of key COVID-19-associated cytokines such as interleukin-6 and tumor necrosis factor." (PMID 33979301, 2021). "Elevated BAL and plasma levels of TNF are a hallmark manifestation of COVID-19, and can be associated with significant morbidity and mortality rates." (PMID 35264975, 2021). "Proinflammatory cytokines, such as tumor necrosis factor-alpha (TNF-α), interleukin-6 (IL-6), IL-1, and IL-8, have been significantly associated with severe COVID-19 cases." (PMID 33714258, 2021). "The high surge of IL6, IL1b, IFNγ, C-reactive protein, and TNF-α senescence leads to lower airway and lung injury and increased risk for COVID-19 in elderly patients." (PMID 33815889, 2021). "It is possible that calcimimetics also mitigate the increases in macrophage TNFα, thereby attenuating the cytokine storm associated with COVID-19, or preventing an impaired neutrophil activation to mount an appropriate anti-viral response." (PMID 34444716, 2021). "It has been demonstrated that the extensive release of inflammatory mediators such as TNF-α, IL-6, and IL-10 is associated with increased mortality risk in COVID-19 patients." (PMID 33997001, 2021). "These included MCP1, IL-6, IL-1β and TNFα, which are typical components of the cytokine storm associated with respiratory failure and high mortality in COVID-19 patients." (PMID 34807265, 2021). "The study on patients with rheumatic disease diagnosed with COVID-19, anti-TNF use was associated with decreased hospitalization chances (OR 0.40, 95 per cent CI 0.19 to 0.81)." (PMID 33937545, 2021). "Our results also illustrated that the serum levels of IL-1β, TNFα, IL-6, IL-12, IL-23, and IL-33 are risk factors associated with COVID-19 severity." (PMID 34917631, 2021). "Specifically in COVID-19-associated systemic inflammation, severe disease is associated with increased levels of cytokines such as interleukin (IL)-6, tumor necrosis factor (TNF)-α, and IL-2R." (PMID 33074525, 2021). "From apathophysiological perspective, COVID-19 is characterized by an overproductionof inflammatory cytokines (IL-6, TNF-alpha), causing systemic inflammation andhypercoagulability, and multiple organ dysfunction syndrome." (PMID 33836039, 2021). "One of the best examples of critical illnesses is COVID-19, which is associated with the excess production of the pro-inflammatory cytokines interleukin-6 (IL-6), tumor necrosis factor-α (TNF-α,) and other cytokines." (PMID 34944517, 2021). "It is currently admitted that severe forms of COVID-19 are associated with a release of cytokines and chemokines such as IL-2, IL-6, IL-7, IL-10, tumor necrosis factor (TNF), and granulocyte colony-stimulating factor (GCSF)." (PMID 34552938, 2021). "Elevation in the level of TNF, a key pro-inflammatory cytokine, is reportedly associated with increased COVID-19 mortality." (PMID 34281182, 2021). "TNF-α, which has been significantly associated to severe cases of COVID-19, has been studied as a driver of vascular dysfunction, atherosclerosis, and heart failure." (PMID 33182653, 2020). "COVID-19 is associated with both immunodeficiency and hyperinflammation, and T cell numbers are negatively correlated with serum IL-6, IL-10 and TNF-α." (PMID 33365277, 2020). "Hyperinflammation in COVID-19 is associated with such an elevation of proinflammatory cytokines, interleukins, and tumor necrosis factor-α (TNF) and a large number of TNF-induced proteins, and granulocyte colony stimulating factor (GCSF or CSF3)." (PMID 32545518, 2020). "In recent studies, international data from SECURE-IBD highlighted the association of corticosteroids with adverse COVID-19 outcomes and the probable safety of anti-TNF." (PMID 33511147, 2020).